CXCR1 (C-X-C motif chemokine receptor 1)
Diseases named in the same sentence as CXCR1 in open-access papers (continued):
Sharing a sentence is not in itself a finding about the gene and the disease.
cancer (continued). "To clarify the roles of CXCLs in the cancer-promoting effects of senescence-induced hPSCs, we used SB225002, a selective CXCR2 antagonist, and SCH-527123, a CXCR1/CXCR2 antagonist, to block the CXCLs/CXCR2 axis." (PMID 36012531, 2022). "By binding to the receptors C-X-C motif chemokine receptor 1 (CXCR1) and C-X-C motif chemokine receptor 2 (CXCR2), IL-8 promotes cancer angiogenesis and metastasis." (PMID 36497451, 2022). "NETs induce gene expression of cancer stem cell marker CD24, and proinflammatory factors, such as IL1β, IL6, IL8, CXC motif chemokine receptor 1 (CXCR1), MMP2, MMP9 in cocultured luminal breast cancer cells." (PMID 35574410, 2022). "SX-682, a CXCR1/2 inhibitor, enhanced the T cell-based immunotherapeutic efficacy and benefited patients with MDSC-infiltrated cancers." (PMID 35585567, 2022). "SB225002, a selective CXCR2 antagonist, and SCH-527123, a CXCR1/CXCR2 antagonist, canceled the cancer-promoting effects of conditioned media from senescent hPSCs." (PMID 36012531, 2022). "NETs enhance the expression of EMT markers ZEB1, Snail and fibronectin, cancer stem cell marker CD44, proinflammatory mediators, such as IL1β, IL6, IL8, CXCR1, MMP2 and MMP9." (PMID 35574410, 2022). "Interactions between interleukin (IL)-8 and its receptors, CXCR1, and CXCR2, serve crucial roles in inflammatory conditions and various types of cancers." (PMID 35202450, 2022). "Reparixin is an antagonist of IL-8 that binds CXCR1 and CXCR2 receptors to prevent neutrophil chemotaxis, thus avoiding graft tissue damage in organ transplantation and cancer, including breast cancer." (PMID 36591453, 2022). "Therefore, targeting CXCR1/2 may be a promising strategy for cancer treatment." (PMID 36497191, 2022). "The results of TCGA analysis showed that CXCR1 and CXCR2 were lowly expressed in LUAD, and patients with the cancer subtype of magnoid tended to express high level of CXCR1 mRNA." (PMID 35768814, 2022). "Both the CXCR1 and CXCR2 chemokine receptors are prognostic biomarkers in many types of human cancers." (PMID 36091114, 2022). "Both CXCR1 and CXCR2 are expressed on granulocytes, monocytes, mast cells, and NK cells, and can also be expressed on cancer cells 91,92." (PMID 36118530, 2022). "Other CXCR1/2 inhibitors such as reparixin, navarixin, and AZD5069 have also been evaluated in clinical trials to treat patients with advanced cancer." (PMID 35585567, 2022). "CTX also inhibits chemokines that bind to CXCR1 and CXCR2 receptors such as CXCL5, CXCL1/2/3, CXCL1a, CXCL6, and CXCL8 (IL-8) that are involved in cancer angiogenesis and metastasis." (PMID 34822613, 2021). "Cancer cells expressed high levels of ligands CXCL1, CXCL2, CXCL3, and CXCL8, signaling to the receptors CXCR1 and CXCR2 expressed by neutrophils." (PMID 33953163, 2021). "The chemokines which act through CXCR1 and CXCR2 participate in numerous cancer processes, and therefore CXCR1/2 inhibitors as well as CXCR2 inhibitors, are considered as potential anticancer drugs." (PMID 33467722, 2021). "The secretion and production of chemokines such as CCL2, CXCR1/2, CXCL12, CXCR4, and CXCL8 play critical roles in cancer development and subsequent metastasis." (PMID 34530822, 2021). "Similar to cancer stem cells, we found that CD44hi IPF MPCs also express high levels of CXCR1 and show that IL-8 increases the expression of stemness markers Sox2 and Oct3/4 and promotes their self-renewal." (PMID 33822772, 2021). "In GC, CXCR1 regulates the activation of AKT and ERK1/2 signal pathways to modulate the malignant biological behaviors of cancer cells." (PMID 34516330, 2021). "Other GDTLs we detected like CXCR1, VASP, ZYX, GPR137 and GOLPH3 were reported as known markers in many cancers." (PMID 33179221, 2021). "In this context, neutralizing antibodies against CXCR1, CXCR2, or CXCL8 suppressed the migration and invasion in a human ESCC cancer cell model induced by CXCL8." (PMID 33390169, 2021).
cancer (continued). "This confirmed a primary role of CXCR1/CXCR2 and their ligands in the recruitment of neutrophils from blood, in agreement with other cancer types." (PMID 32664318, 2020). "This is reminiscent of the role of another chemokine receptor, CXCR1, which binds some ELR chemokines and is critical for the functionality of cancer stem cells." (PMID 32727083, 2020). "Extensive genes have been identified as the target of miR-761 in numerous cancers, including HDAC1, Rab3D, Runx3, Mitofusin-2, CXCR1, TRIM29, MSI1, ING4, TIMP2, and GSK3β." (PMID 32185226, 2020). "For example, administration of the anti-cancer reagent induced CXCL8 production, and the expression of the receptors of CXCL8, CXCR1 and CXCR2." (PMID 32766720, 2020). "Previous literature data support the concept that CXCR1 induced activation of the PI3K/p-Akt pathway, which is a crucial event in the regulation of cytoskeleton rearrangement and cell mobilization in cancer." (PMID 31986121, 2020). "CXCR1 and IL11R represent potential therapeutic targets since they promote macrophage survival and induce apoptosis resistance in cancer cells and also stimulate cancer cell survival and promote angiogenesis and metastasis formation, respectively." (PMID 30967156, 2019). "IL-8 and its receptors, CXCR1 and CXCR2, have been extensively reported to mediate invasion, angiogenesis, and metastasis of various cancers." (PMID 31684995, 2019). "This bystander effect was demonstrated in breast CSCs resistant to chemotherapy by the secretion of IL8 by dying cancer cells that signaled survival signals via the IL8 receptor, CXCR1, on the CSCs." (PMID 29861860, 2018). "Unbiased analyses identified cancer-elaborated CXCL1/PPBP, potent myeloid cell chemoattractants that drive inflammation and metastasis via CXCR1/CXCR2 on host cells, as the transcriptional targets of IL-1β-fostered KRAS-IKKα addiction." (PMID 29445180, 2018). "IL-8 mediates its biological effects through two cell-surface G protein-coupled receptors, termed CXCR1 and CXCR2, found on cancers cells, endothelial cells, neutrophils, and TAMs." (PMID 28545495, 2017). "Previous reports revealed that CXCR1 knockdown reduces chemotherapy-induced CRT exposure in cancer cells, and that CXCL8 facilitates formation of the CRT/CXCR1 complex." (PMID 28938588, 2017). "Increased IL-8 of prostate cancer cells signals through CXCR1 and CXCR2 to induce transcription of androgen receptor (AR) and to activate ERK and Akt, in turn, promoting cancer growth and survival." (PMID 29379802, 2017). "This study also showed that IL-8 in vitro attracted CXCR1- and CXCR2-expressing MDSCs isolated from cancer patient peripheral blood mononuclear cells, and that IL-8 induced extrusion of neutrophil extracellular traps from MDSCs with a granulocytic phenotype." (PMID 27348007, 2016). "Recently, several studies indicated that specific blockade of CXCR1 or CXCR2 with neutralizing antibodies resulted in different inhibition of CSC population and cancer cell growth." (PMID 25871388, 2015). "IL-8 confers its effects on cellular phenotypes upon binding to its two cell surface cognate receptors, CXCR1 and CXCR2, which are widely expressed on the cancer as well as endothelial cells." (PMID 25970774, 2015). "During cancer growth, vascularization is a key factor to support the development of tumors, wherein CXCL8 induces endothelial growth through CXCR1 and CXCR2 signaling." (PMID 26087179, 2015). "In monocytes, an increase in CXCR4 expression has been shown in CD14+CD16− cells cultured with cancer cells, alongside increases in the expression of CCR2, CXCR1 and CXCR2." (PMID 25251539, 2014). "In each case, administration of the anti-cancer agent was shown to induce CXCL8 expression and secretion, as well as expression of the CXCR1 and CXCR2 receptors." (PMID 24276377, 2013). "As an angiogenic chemokine, CXCL8 binds with high affinity to both the CXCR1 and CXCR2 receptors, contributing to its function in the cancer microenvironment." (PMID 24224100, 2013).
cancer (continued). "The IL-8 chemokine activates multiple pathways following its engagement with two G protein receptors (CXCR1 and CXCR2), leading to the promotion of the proliferation, survival, and migration of cancer cells." (PMID 23632023, 2013). "Through the G protein-coupled receptors CXCR1 and CXCR2, it exerts both inflammatory and angiogenic responses, and can directly stimulate cancer cell proliferation and survival." (PMID 22353811, 2012). "We therefore tested an alternative Ccr7 inhibition approach using navarixin, a small molecule negative allosteric modulator of Ccr7, Cxcr1, and Cxcr2 that has been studied in clinical trials for airway disease and cancer indications." (PMID 39969509, 2025). "Similarly, CXCR1/CXCR2 inhibition with the small molecule inhibitor ladarixin diminished the presence G-MDSCs near EY epithelia basement membranes and decreased carcinoma incidence and burden in EY mice." (PMID 39779672, 2025). "Additionally, we examined the expressions of IL-8, CXCR1, and CXCR2, which we previously reported, and MMP9 expression of cancer nests in the human ESCC tissues." (PMID 37296952, 2023). "This is lightly investigated in TNBC in vitro using CXCR1 or CXCR2 antibodies but was not investigated in each cancer type nor in vivo." (PMID 36831112, 2023). "Concerning this latter, include, (but are not limited to): C-X-C Motif Chemokine Receptor 1 (CXCR1) and CXCR2 (promote the recruitment of TANs to cancer); CXCL8, CXCL6 and CXCL5; Tumour Necrosis Factor alpha (TNF-α); Gamma-delta T cells (γδ T cells)-derived IL-17 (Interleukin-17)." (PMID 35406451, 2022). "The inability of each receptor to compensate for the absence of the signals delivered by the other receptors suggests that all receptors, CXCR1/2 + CCR2 + CCR5, needed to be activated simultaneously in order to mediate the intrinsic signals of WT-PD-L1 that lead to increased cancer cell invasion." (PMID 35205789, 2022). "CXCR1 and CXCR2 are reported to promote proliferation and invasion in many cancer cells." (PMID 34277625, 2021). "Furthermore, some studies showed IL-8 or chemokine (C-X-C motif) ligand 8 (CXCL8) receptor, C-X-C Motif Chemokine Receptor 1 (CXCR1) or CXCR2, altered CARs significantly enhance the invasion and persistence of T cells in cancer environment." (PMID 33167514, 2020). "Moreover, CXCR1 and CXCR2 expressed on immune cells can promote the recruitment of cancer microenvironment, thus affecting cancer invasion and metastasis." (PMID 33324682, 2020). "Importantly, CRC association was found for two genes in the previously reported 2q25 locus, CXCR1 and CXCR2, which are potential cancer therapeutic targets." (PMID 30820706, 2019). "Other experimental approaches targeting MDSCs in the concept of cancer include the blockade of accumulation pathways like the CCL/CCR2 axis and IL-8/CXCR1/2 interactions, which may hinder the trafficking of MDSCs to the TME and inhibit extravasation." (PMID 31847487, 2019). "Additionally, some investigations showed that mast cells also expressed chemokine receptors such as CXCR1 and CXCR2 in different cancers." (PMID 30808413, 2019). "Clinical trials evaluating reparixin, a CXCR1 and CXCR2 inhibitor, are ongoing in cancer patients." (PMID 30304046, 2018). "In addition to IL-8, its receptors CXCR1 and CXCR2 were also reported in human PDAC Capan-1 cells to regulate cancer cell growth, migration, invasion, and its stem cell-like features." (PMID 29379802, 2017). "Interestingly, CXCR1 expression was largely restricted to the lung endothelium, and NRAS‐mutant cancer cells exhibited a specific pulmonary metastatic pattern likely dictated by their chemokine expression profile, similar to other pro‐metastatic axes." (PMID 28341702, 2017). "Both IL-8 antibody and CXCR1/CXCR2 antibody combination significantly reduced the sphere number and size of G9a-overexpressing cells indicating that IL-8 is a mediator for G9a to promote cancer stemness via an IL-8/CXCR1/2 signaling axis." (PMID 27531902, 2016).
cancer (continued). "The presence of CXCR1-bright cells in the prostate stroma was observed for 50% of non-obese and for 75% of obese patients with high-grade cancer." (PMID 27241286, 2016). "Both CXCR1 and CXCR2 predominately expressed in cancer tissues." (PMID 26087179, 2015). "Furthermore, some examples of hypomutated proteins represent known cancer-related proteins, such as cytokine receptors CCR5 and CXCR1." (PMID 26565620, 2015). "CXCR1 and CXCR2 can mediate migration, invasion, and proliferation individually in cancer cells." (PMID 25852766, 2015). "Moreover, IL-8 receptor, CXCR1, is also specially expressed in an ALDH-positive cancer cell sub-population and these cells are resistant to FASL-induced apoptosis." (PMID 25871388, 2015). "CXCL8 is a proinflammatory chemokine that acts on leukocytes and endothelial cells, via their CXCR1 and CXCR2 receptors, to promote immune infiltration and angiogenesis, which in turn establishes a venue for cancer cell local invasion, migration, and metastasis." (PMID 24224100, 2013). "The CXCR1/2 receptor/ligand pathway also regulates the activity of the activation of MAPK signaling cascade, with downstream phosphorylation of ERK1/2 detected in cancer cells." (PMID 23420470, 2013). "The past decade has witnessed the generation and development of antagonists to CXCR1 and CXCR2, and multiple clinical trials are underway investigating the therapeutic potential of targeting this signaling axis in inflammatory disorders and cancers (NCT03161431, NCT04245397, NCT03400332)." (PMID 37270599, 2023). "However, it remains controversial as to whether there is a direct function of either or both CXCR1 and CXCR2 on the growth of the cancer cells, and if so, which of these receptors are involved and what mechanisms are employed." (PMID 37270599, 2023). "As inhibition of IL8 receptor CXCR1/2 with reparixin diminished CSC tumorsphere forming and cancer cell migration induced by autocrine inflammatory forward-feedback loop, we then asked whether reparixin would inhibit CSC enrichment after paclitaxel withdrawal in vitro." (PMID 28703802, 2017). "Another report showed that CXCR1 could up-regulate matrix metalloproteinase-9 (MMP-9) expression by activating JNK/c-Jun and ERK/Ets-1 pathways, thus resulting in more aggressive biological characteristics of cancer cells." (PMID 27780937, 2017). "Therefore, the simultaneous application of CXCR1/2 inhibitors and HER2 inhibitors in cancer therapy can inhibit the tumor-promoting activity of TAMs, inhibit the proliferation and migration of CSCs, and improve the overall survival rate of patients with cancer." (PMID 35740975, 2022). "Reparexin is a noncompetitive allosteric inhibitor of the IL-8 receptors CXCR1 and CXCR2, and its cytotoxic effects on cancer cells at different concentrations were not significantly different." (PMID 39905539, 2025). "In our study, the expression levels of both CXCR1 and CXCR2 in cancer nests were not related to prognosis." (PMID 29285315, 2017).
infection (60 papers, 2010 to 2025). The state of being infected such as from the introduction of a foreign agent such as serum, vaccine, antigenic substance or organism. "The fundamental role of CXCR1 in fighting infections is further confirmed in humans carrying a genetic variant of CXCR1 (CXCR1–T276) that have increased bacterial infections." (PMID 32733442, 2020). "The loss of CXCR1 expression may have resulted in a failure to provide sufficient protection to the growing foetus against infection in pregnancy." (PMID 35453930, 2022). "In addition, the viral chemokine vCXCL1, which is encoded by CMV, preferentially binds to CX3CR1 and CXCR1, and mediates the migration of CD56dim cells to the site of infection." (PMID 34452400, 2021). "Moreover, the data show that CXCR1/2 antagonism clearly decreased inflammation association with the infection and resulted in a more favorable outcome." (PMID 29326698, 2017). "The PPI observed that the hub genes with the largest number of associated nodes in the weighted network played a crucial role in the immune cell recruitment and activation after infection, such CXCR1, VNN2, BST1, CREM, IL1R1, and CD48." (PMID 39692191, 2025). "The chemotaxis of neutrophils towards the infection site depends on the binding of CXCL-8 to the G protein-coupled cell surface receptors CXCR1 and CXCR2 expressed by infected epithelial cells." (PMID 40475997, 2025). "Proinflammatory cytokines IL-6 and IL-1α were significantly upregulated post-infection, while IL-8 and CXCR1 were differentially expressed, indicating their involvement in neutrophil recruitment and immune modulation." (PMID 40453956, 2025). "Gene expression of interleukin (IL)-6, IL-8, TLR2, TLR4, IL-1 alpha (IL-1α), and CXCR1 was evaluated by quantitative real-time polymerase chain reaction at 0, 6, 12, 24, 48, and 72 h post-infection." (PMID 40453956, 2025). "Although the overall expression level of CXCR1 was lower than that of other immune genes, its expression consistently increased from the 0-h mark through to 72 h post-infection." (PMID 40453956, 2025). "The activation of these receptors promotes the migration of immune cells to sites of infection or inflammation, making the CXCL8/CXCR1-2 axis crucial in the host response to infections." (PMID 39962077, 2025). "The genes encoding the chemokine receptors CXCR1 and CXCR2 were also upregulated in the HC fed cows; these are both important in stimulating chemotaxis of PMN toward sites of infection as well as activating biochemical processes that kill invading bacteria." (PMID 36613482, 2022). "Recently, CXCR2 was reported to be the functional receptor for CXCL8_L1 in zebrafish where it is known to be involved in neutrophil recruitment during local infections, even though both CXCR1 and CXCR2 are expressed in neutrophils." (PMID 24613851, 2014). "Granulocytes have high constitutive expression of the CXCR1 gene, which presumably allows rapid mobilization of these cells in response to infection." (PMID 20865040, 2010). "Interestingly, our results demonstrated that interaction scores of some paired ligands and receptors (e.g., ANXA1_FPR1, CD74_APP, CD74_COPA, CXCL1_CXCR1, CXCL2_CXCR2, and HLA-F_LILRB2) were significantly increased after infection." (PMID 37087411, 2023). "As infection progressed, we detected a robust upregulation of genes encoding cytokines and chemokines (CCL2, CCL3, IL1B, CXCR1, IL1RN) as well as granulocyte associated transcripts (TLRs 1-4, SPI1, S100A8, S100A9, CD177), which correlated with the higher numbers of granulocytes 5 DPI." (PMID 28852031, 2017). "In the rare event that an individual is administered a CXCR1/2 blocker soon after infection, increased WNV replication in the periphery could result in a more aggressive disease outcome." (PMID 25324719, 2014).